DEFB129 (defensin beta 129)
Description:
Has antibacterial activity.
Synonyms: DEFB-29; C20orf87; DEFB29; bA530N10.3; hBD-29
Tractability: Antibody: UniProt places it where antibodies can reach, with high confidence; UniProt predicts a signal peptide or a membrane-spanning region; its Gene Ontology location is reachable by antibodies, with medium confidence.
Gene: Protein-coding gene on chromosome 20 (227,258 to 229,886, forward strand). Ensembl gene ENSG00000125903.
Subcellular location: Secreted
Pathways (Reactome):
Immune System: Beta defensins; Defensins
Gene Ontology:
Molecular function: protein binding
Cellular component: extracellular region
Genetic constraint (gnomAD): Loss-of-function variants: 2 observed, 4.07 expected, observed/expected ratio (o/e) 0.49, 90% interval 0.2 to 1.48. That is too few expected variants to judge how well the gene tolerates losing a copy. Missense variants: 177 observed, 228.54 expected, observed/expected ratio (o/e) 0.77, 90% interval 0.68 to 0.88. Synonymous variants: 76 observed, 78.8 expected, observed/expected ratio (o/e) 0.96, 90% interval 0.8 to 1.17.
Homologues: Orthologues: chimpanzee DEFB129 (100% identical), macaque DEFB129 (95% identical), dog DEFB129 (58% identical), pig DEFB129 (54% identical), rabbit DEFB129 (51% identical), mouse Defb23 (39% identical), rat Defb23 (38% identical). Paralogues in human: DEFB125 (16% identical), DEFB116 (12% identical), DEFB121 (12% identical), DEFB127 (12% identical), DEFB128 (11% identical), DEFB132 (11% identical), DEFB104A (11% identical), DEFB104B (11% identical), DEFB115 (11% identical), DEFB118 (11% identical), DEFB123 (11% identical), DEFB108B (10% identical), and 7 more.
Diseases named in the same sentence as DEFB129 in open-access papers:
DEFB129 is named in the same sentence as 6 diseases in open-access papers, as found by Europe PMC text mining. Sharing a sentence is not in itself a finding about the gene and the disease.
DEFB129 shares sentences with these, for which no sentence is quoted: tumor (11 papers); ovarian carcinoma (9); cancer (3); ovarian tumors (3); melanoma (2); lung carcinoma (1).